STAT3 (signal transducer and activator of transcription 3)
Diseases named in the same sentence as STAT3 in open-access papers (continued):
Sharing a sentence is not in itself a finding about the gene and the disease.
tumor (continued). "We posit that the ERO1α/IL-6/STAT3/SLC7A11 pathway is critical for mTORC1-mediated ferroptosis resistance and tumor growth and that it can be targeted for the treatment of cancers associated with dysregulated mTORC1 signaling." (PMID 38610018, 2024). "There is strong evidence that the interaction between cancer-specific Bcl-2, STAT3/NF-κB signaling and the recruitment of M2-TAM promote a pro-tumor microenvironment." (PMID 39061137, 2024). "In comparison, our study on Y-A shows a more pronounced inhibition of STAT3 and JAK phosphorylation, which suggests a potentially stronger effect on tumor cell proliferation and immune response modulation." (PMID 39056720, 2024). "To further confirm SRI and STAT3 expression, we collected clinical samples of HCC and adjacent non-tumor tissues to perform Western blot." (PMID 39000312, 2024). "Numerous studies have demonstrated the crucial involvement of JAK/STAT1, JAK/STAT3, and JAK/STAT5 signaling pathways in tumor progression." (PMID 38894865, 2024). "Our results revealed that GeXIVA suppressed TNBC tumor growth via the inhibition of AKT-mTOR, STAT3 and NF-κB-mediated proliferation." (PMID 38921563, 2024). "Niclosamide suppresses STAT3 and AKT signaling specifically in ALDH1A1+ CSCs, augmenting tumor response to androgen deprivation." (PMID 38800385, 2024). "ASRPS can inhibit tumor progression and the mechanism is that the ASRPS peptide binds STAT3 directly through the coiled coil domain (CCD), and then down-regulates the phosphorylation of STAT3, resulting in a decrease in the expression of VEGF." (PMID 39030557, 2024). "By means of the JAK2/STAT3 signaling pathway, SIRT6 can inhibit tumor cell growth by inducing apoptosis and diminishing oxidative stress." (PMID 39408693, 2024). "The overexpression of IGF-1R during tumor development activates downstream signaling pathways such as AKT, ERK1/ERK2 and STAT3." (PMID 38686058, 2024). "The activated STAT3 protein contributes to cell growth, differentiation, and the upregulation of VEGF expression, leading to induction of tumor angiogenesis." (PMID 38611849, 2024). "This investigation underscores the central role of STAT3 as a regulator in ESCC, directly impacting LHPP expression and suggesting a regulatory loop crucial for tumor behavior." (PMID 39468431, 2024). "Previous studies demonstrated that OPN is a direct target of the transcription factor Stat3, an important regulator in establishing an immune suppressive TME that is crucial during tumor recurrence." (PMID 39448577, 2024). "In Pten‐null senescent tumours, the JAK2/STAT3 pathway was activated, resulting in the secretion of CXCL1, CXCL2 and IL‐6, thereby promoting macrophage M2 polarisation." (PMID 39270064, 2024). "Many clinical studies have been exploring the potential of STAT3 and TGF-β signal inhibitors targeting the tumor stroma or microenvironment, but so far the efficacy of these inhibitors has been very limited." (PMID 38467634, 2024). "It has been shown that RACK1 is closely related to tumor progression due to its modulation of multiple signaling pathways including PKC, receptor tyrosine kinase/PI3K/AKT, ERK/MAPK, STAT3, Src/FAK, NF-κB, Wnt/β-catenin, and RhoA/Rho pathway." (PMID 38398158, 2024). "For instance, miR-216b, a tumor suppressor miRNA, targets JAK2/STAT3 signaling via HMGB1 overexpression in CRC." (PMID 38185635, 2024). "It was shown that STAT3 and STAT5 are involved in tumor initiation and progression, while STAT1 and STAT2 play an essential role in anti-tumor defense and long-term immune response." (PMID 39136000, 2024). "CD109 induces EGFR-mediated STAT3 phosphorylation, which supports SCC cell migration, proliferation, and the cancer stem cell phenotype, highlighting its role in enhancing tumor aggressiveness and inflammation." (PMID 39990858, 2024).
tumor (continued). "cPD‐L1 not only helps tumor cells evade the cytotoxic effects of chemotherapy and radiotherapy, but also modulates several inflammatory responses, including COX2 and STAT3, which promote the survival and growth of tumors." (PMID 37934012, 2024). "STAT3 interacts with other oncogenic transcription factors (e.g., GLI1) to promote tumor aggressiveness in TNBC." (PMID 39735530, 2024). "MiR-124, another tumor suppressor, inhibits CRC cell proliferation and induces apoptosis by directly inactivating STAT3 in vitro and in vivo." (PMID 38185635, 2024). "In tumor cells, interleukin-6 (IL-6) signaling can lead to activation of the epidermal growth factor receptor (EGFR), which prolongs Stat3 activation." (PMID 39000275, 2024). "Myeloid calcineurin promotes NFAT-dependent IL-6 transcription, which then acts on tumour cells and supports epithelial B7H3 and B7H4 expression in a STAT3-dependent manner." (PMID 39061159, 2024). "Signal Transducer and Activator of Transcription 3 (STAT3) has been shown to play an important role in tumorigenesis and progression by regulating cell proliferation, differentiation, metastasis and apoptosis, which might be one of the main targets for tumor therapy." (PMID 38509141, 2024). "Residual tumour cells post NACT were enhanced for several relevant pathways including DNA damage, Apoptosis, IL6-Jak-Stat3, Hedgehog, Wnt beta catenin signalling, and inflammatory response whilst a mitosis gene set was reduced." (PMID 39341888, 2024). "While STAT3 has been extensively studied in solid tumors, including GBM, less is known about the role of STAT5A and STAT5B in tumor progression." (PMID 38892466, 2024). "Tumor cells promote CAF generation, and the CAFs, in turn, improve the invasiveness and metastasis of the malignant T cells through the IL-6/JAK2/STAT3/SOX4 or IL-6/HIF-1α/SOX4 pathway." (PMID 39963655, 2024). "This synergy is significant, as KTN not only stabilizes OVV within the tumor microenvironment but also modulates key pathways like STAT3, dnhancing OVV’s ability to suppress tumor growth and metastasis." (PMID 39519023, 2024). "Treatment with the small-molecule STAT3 inhibitor BBI60830 significantly reduced tumor size, suggesting that the growth of KPT mutant tumors is fueled by STAT3." (PMID 39128004, 2024). "The results clearly demonstrated that the silencing of both STAT3 and ACC1 led to a significant inhibition of tumor growth." (PMID 38495496, 2024). "Together, our study demonstrates a signaling axis involving STAT3/FGF7/AKT that mediates the crosstalk between CAFs and ccRCC tumor cells, providing valuable insights for treating ccRCC patients." (PMID 39594574, 2024). "Ginsenoside Rh2 inhibited tumor growth in TNBC mice and reduced the expression of IL- 6, IL-6R, STAT3, Bcl-2, and Bcl-xL in tumor tissues." (PMID 39845783, 2024). "Thus, STAT3 unresponsiveness might compromise the anti-tumor effect of Erdafitinib in LUSC." (PMID 39247610, 2024). "The exosomes from breast cancer cells overexpressing O-type protein tyrosine phosphatase receptor (PTPRO) induce the polarization of M1 macrophages by mediating the dephosphorylation of STAT3 and STAT6, which reduce migration and invasion of tumor cells." (PMID 38633106, 2024). "Studies have shown that tumour-derived exosomal HSP72 stimulates the expansion of MDSCs through Erk and activates STAT3 by inducing autocrine IL-6 in a TLR2/MyD88-dependent manner." (PMID 38302430, 2024). "In different tumor cells, TREM2 expression levels vary significantly and can promote or inhibit tumor progression through different signaling pathways, such as NF-κB, JAK/STAT3 and PI3K/Akt signaling pathways." (PMID 38725629, 2024). "Consistently, in our study, we proved that PL resulted in the reduction of the p-PI3K/p-AKT/p-mTOR/JAK2/p-STAT3 and the augment of the p-p38/p-ERK1/2/p-JNK in the H22 tumor-bearing mice." (PMID 38240856, 2024).
tumor (continued). "IL-6, IL-8 have been reported to induce chemoresistance in cancer through activation of the Jak2/Stat3 signaling pathway, activation of Stat3 can further promote VEGF expression and induce tumor angiogenesis." (PMID 39193386, 2024). "Th17 cells produce IL-17A, which facilitates cancer cell migration, invasion, and stemness through the STAT3/NF-κB/Notch1 signaling pathway, while also recruiting MDSC cells in the TNBC tumor microenvironment, further enhancing tumor progression." (PMID 39867914, 2024). "To test the relative importance of the STAT3 and TGF-β pathways to tumor morphology and functionality, we generated STAT3/SMAD4 and STAT3/TGFBR2 double knockout (DKO) cell lines." (PMID 38573819, 2024). "We observed a positive correlation between tumor size and weight with the levels of WNT7A expression and Y705 phosphorylation of STAT3." (PMID 38246919, 2024). "Overall, the mTORC1/ERO1α/IL-6/STAT3/SLC7A11 signaling cascade, which is also present in human cancer cells, plays a critical role in ferroptosis resistance and tumor progression." (PMID 38610018, 2024). "Our results found EFNA3 boosted CM cells’ growth and migration through activating Stat3/Akt signaling pathway, while ART inhibited the tumor promoting effect of CM via downregulating EFNA3." (PMID 38630320, 2024). "By targeting STAT3, BTK, and MEK pathways, these inhibitors can effectively enhance anti-tumor effects, providing an alternative to CD20 therapy with fewer adverse reactions." (PMID 39519376, 2024). "LLL12B was tested in TNBC cells, and the results showed that targeting STAT3 with LLL12B induced apoptosis and suppressed colony formation, migration, and tumor growth in TNBC cells." (PMID 38892472, 2024). "The tumor slices from human CRC SW480 and HT-29 xenografts were subjected to assessment of the IL-6R signaling pathways, including phosphor-STAT3 and phosphor-Erk-1/-2 levels in the untreated and treated groups." (PMID 38256960, 2024). "As the main components of HCC tumor matrix, CAFs enhance the dry of CD24+ cells and promote HCC progression by activating HGF and IL6 secreted by STAT3 Tyr705 phosphorylation." (PMID 39679376, 2024). "In the tumor microenvironment, CXCLs/CXCR-2 cascade can signal through RAS/ERK, PI3K/AKT/mTOR, PKC/p38/NF-κB, JAK/STAT3 and PLD to regulate DNA damage, senescence, angiogenesis, survival, proliferation, migration and further administration of chemokines." (PMID 38672477, 2024). "Further, we identified that integrin signaling, tumor microenvironment pathways, ERK/MAPK pathways, regulation of EMT, STAT3 signaling etc. were the highly enriched pathways in the differentially upregulated genes in the OVCAR8-CisR spheroid dataset." (PMID 38839865, 2024). "CTLA4apt-STAT3, a CTLA4 aptamer that delivers STAT3 siRNA to tumor cells, CD8+ T cells and Treg cells, finally inducing activation of the antitumor immunity." (PMID 38245798, 2024). "IGFBP-2 can also act intrinsically by interacting with integrin receptors, which can involve regulation of downstream effectors such as the tumour suppressor genes PTEN, STAT3, and NFκB." (PMID 38893232, 2024). "In this case, Mw treated tumors accumulated Tregs, which neutralized the anti-tumor immune response via TGF-B and IL-10 dependent ERK-1/2 MAPK and STAT3 activation in TAM." (PMID 39534596, 2024). "Targeting STAT3 can improve the efficacy of TLR9 agonist-based immunotherapy, being a checkpoint or the ‘brake’ for anti-tumor immune responses." (PMID 38245798, 2024). "Paradoxically, research has demonstrated that despite their contradictory nature, both STAT3 and STAT5 can function as tumor suppressors." (PMID 38686058, 2024). "JNK1 promotes TBP production and thus tumor development and inhibits apoptosis through JNK1/STAT3 signaling." (PMID 38800967, 2024).
tumor (continued). "Interestingly though, a survey of the anti-tumor activity of SP2509 reported that SP2509 could inhibit JAK/STAT3 signaling and related downstream gene expression dependent on its original target LSD1 in cancer cells, which in turn was tied to the innate immune response of the host cell." (PMID 38730463, 2024). "Previous research has highlighted the role of STAT3 in facilitating lipid transport via CD36, thus supplying ample energy for tumor cell proliferation and migration." (PMID 38495496, 2024). "This reprogramming is driven by the induction of the STAT3 and STAT5 pathways, triggered by tumor-derived cytokines such as G-CSF and GM-CSF, which upregulate the expression of fatty acid transporter protein 2 (FATP2)." (PMID 39227970, 2024). "By modulating STAT3 activity, KTN enhances the antitumor efficacy of the OVV through better immune modulation and direct tumor cell targeting." (PMID 39519023, 2024). "The ERO1α/IL-6/STAT3/SLC7A11 pathway is crucial for mTORC1-mediated ferroptosis resistance and tumor growth, and combining ERO1α inhibition with ferroptosis inducers is a novel and effective treatment for mTORC1-related tumors." (PMID 38610018, 2024). "As such, the combined inhibition of STAT3, a protumorigenic signal activated in TLR9-stimulated tumor cells, with CPG-ODNs led to the suppression of subcutaneous or intratibial castrate-resistant prostate tumors in mice." (PMID 38201300, 2024). "Based on the current research, LIF aids in tumor growth and invasiveness by preventing differentiation and activating the JAK/STAT3 pathways." (PMID 39451257, 2024). "Previous research has highlighted lncRNA’s participation in multiple signalling pathways, such as Wnt/β-catenin, TGF-β/Smad, STAT3 and VEGFA/VEGFR2, consequently influencing tumour invasion and metastasis, tumour angiogenesis." (PMID 39267831, 2024). "Another study also showed that MSC-derived EV, prostaglandin D2 synthase (L-PGDS) reduced the levels of stem cell markers (such as Oct4, Nanog, and Sox2) and suppressed the phosphorylation of STAT3, thereby affecting CSC properties and tumor progression." (PMID 39578849, 2024). "Through complex interactions with molecules such as DARPP-32, STAT-3, CXCR4, and CXCL-12, dopamine contributes to cancer cell invasion, immune response modulation, and tumor growth by stabilizing key proteins involved in angiogenesis and metastasis." (PMID 39767693, 2024). "Apart from NCAPD3 regulation of STAT3, we also reported before that NCAPD3 upregulated other TFs like MYC and EZH2 to promote tumor progression." (PMID 38561330, 2024). "In cancer cells, apelin signaling has been shown to promote tumor growth through mechanisms involving the PI3K/Akt pathway, as well as the activation of Notch3 and STAT3." (PMID 39684225, 2024). "The strongest hits in this prior study included the transcription factors STAT1 and STAT3, demonstrating a role for JAK-STAT signaling in regulating tumor CD38 expression within the bone marrow microenvironment." (PMID 40453054, 2024). "Signal Transducer and Activator of Transcription 3/5 (STAT3, STAT5) can act as oncogenes or tumor suppressors in the context of tissue types." (PMID 39136000, 2024). "GSEA revealed that CBX3 knockdown modulated expression of genes related to tumor escape from immune attack, KRAS signaling, IL-6 receptor-ligand interaction, and STAT3 activity." (PMID 39545414, 2024). "Its influence on the TIME includes two aspects: one promotes the activation of TIL-B, resulting in its anti-tumor activity; the second suppresses the expression of tumor suppressors (RB and p21) and oncogenic proteins (Kras, Akt, ERK, STAT3, CDK6, and CDK4)." (PMID 38361933, 2024). "IL‐6 also activates STAT3 promoter gene transcription through JAK, promoting cell proliferation and preventing cell apoptosis, leading to tumour formation." (PMID 38961677, 2024).
tumor (continued). "At the molecular level, M2-TAMs induced by iCCA cells promote tumor growth and invasion through the EMT signaling pathway involving IL-10 and STAT3, suggesting a potential new target for iCCA therapy." (PMID 39290697, 2024). "On the other hand, inhibition of the JAKs/STAT3 signaling pathway induced apoptosis in CRC cells leading to tumor cell invasion and tumor growth restrain." (PMID 39136000, 2024). "By contrast, STAT3, which is activated by S1P1 in several tumor cell lines, remained quiescent in S1P1-overexpressing macrophages." (PMID 39531328, 2024). "Mechanistically, W. coagulans MZY531 postbiotics inhibit tumor growth through the modulation of the Bax/Bcl-2/caspase-3 and JAK2/STAT3 apoptosis pathways and PI3K/AKT/mTOR and TGF-β/SMAD4 cell autophagy pathways." (PMID 39459634, 2024). "Expression of PTPRO was negatively correlated with p-JAK2, p-STAT3, Bcl-2, and Snail levels in LUAD tumor samples." (PMID 38182570, 2024). "We also found that B-ISG15 was enriched in the IL2 STAT5 signaling and IL6 JAK STAT3 signaling gene sets, and IL-6/JAK/STAT3 signaling drives tumor cell proliferation, survival, invasion, and metastasis while inhibiting the antitumor immune response." (PMID 38216927, 2024). "This study highlights that dysregulated NF-κB and STAT3 signalling contributes to the observed inflammatory signature found within TSC cell line models and in TSC patient tumours." (PMID 39070657, 2024). "In colorectal cancer, phosphorylated ATF6 has been demonstrated to promote tumor development by inducing gut microbiome dysbiosis and activating the TIR domain-containing adapter-inducing interferon-β (TRIF)/STAT3 signaling cascade." (PMID 39080273, 2024). "As HER2/3 phosphorylation leads to tumor progression and resistance, a multifunctional nanoparticle formulation of afatinib and miR-139 targeting EGFR/HER/Ras/Akt/Rac1/STAT3/MAPK/EMT/Bcl-2 pathways has been found to suppress metastasis in CRC cells." (PMID 38339403, 2024). "To assess the role of STAT3 in KRAS-driven tumorigenesis, we measured proliferation rates, contact inhibition, and tumor formation in mice." (PMID 38573819, 2024). "Surprisingly, salidroside significantly up-regulated the expression of tumor suppressor miR-1343-3p, and down-regulated the expression of MAP3K6, STAT3 and MMP24-related genes." (PMID 38436092, 2024). "Signal transducer and activator of transcription 3 (STAT3), as a key node in numerous carcinogenic signaling pathways, is activated in various tumor tissues and plays important roles in tumor formation, metastasis, and drug resistance." (PMID 38172648, 2024). "Inhibition of JAK2/STAT3 signaling induces CRC cell apoptosis and cell cycle arrest, and suppresses tumor growth and invasion in CRC." (PMID 38673975, 2024). "STAT can act cooperatively, and the activation of STAT3 and STAT6 increases cathepsin expression in TAMs, promoting tumor invasion in vivo." (PMID 39516356, 2024). "STAT3 promotes signaling through pro-oncogenic inflammatory pathways, such as NF-kB and gp130/Jak/STAT, leading to increased tumor cell proliferation, survival, and invasion while simultaneously suppressing antitumor immunity." (PMID 38799159, 2024). "Mechanistically, circLOC729852 facilitates the recruitment and M2 polarization of TAMs by upregulating IL‐10 via activation of the JAK2/STAT3 pathway, and the M2 TAMs promote BLCA progression by inducing IL‐10 expression in the tumour cells." (PMID 38506082, 2024). "It has been demonstrated that AA takes part in inhibiting phosphorylation, inducing cell death, and reducing tumor growth and metastasis by influencing important signaling pathways, such as PI3K, Akt, mTOR, p70S6K, and STAT3, in cancer cells." (PMID 38610995, 2024). "Activation of multiple pathways, including NF-κB, JAK/STAT3, and PIK3/Akt, in tumor cells promotes PMT." (PMID 37692522, 2024).